SMAD2 (SMAD family member 2)
Diseases named in the same sentence as SMAD2 in open-access papers (continued):
Sharing a sentence is not in itself a finding about the gene and the disease.
Hodgkins lymphoma (1 paper, 2021). A heterogeneous group of malignant lymphoid neoplasms of B-cell origin characterized histologically by the presence of Hodgkin and Reed-Sternberg (HRS) cells in the vast majority of cases. "At the same time, EBNA1 can promote the degradation of Smad2 protein and inhibit the transcription of TGF-β target gene protein tyrosine phosphatase receptor κ (PTPRK), thereby promoting the growth and survival of Hodgkin lymphoma (HL) cells." (PMID 33549103, 2021).
hydatidosis (1 paper, 2022). "The present study suggests that SMAD2 and SMAD3 have certain clinical relevance to hydatidosis in young children." (PMID 36443650, 2022). "The expression levels of TGF-β, SMAD2, SMAD3, SMAD4, and leukemia inhibitory factors (LIF) in the cystic fluid and the corresponding paracystal tissues of infected viscera or tissues in children with hydatidosis were measured using the ELISA kit." (PMID 36443650, 2022). "SMAD2 and SMAD3 have a certain clinical relevance with hydatidosis in young children." (PMID 36443650, 2022).
idiopathic inflammatory myopathies (1 paper, 2023). "These were CLCC1 whose loss yields muscle myotonia, HLA-A/B that disappears during myogenesis and is linked as a risk factor for idiopathic inflammatory myopathies, and SMAD2 that shuts down myoblast fusion." (PMID 36282542, 2023).
juvenile polyposis (1 paper, 2022). "Although juvenile polyposis patients have been screened for SMAD2 and SMAD3 mutations, only SMAD4 germline mutants are identified as an underlying cause of juvenile polyposis." (PMID 36267157, 2022).
Loeys-Dietz syndrome 6 (1 paper, 2025). "Heterozygous mutations in SMAD2 cause two major autosomal dominant disorders: congenital heart disease-8, with or without heterotaxy (CHTD8), and Loeys-Dietz syndrome-6 (LDS6)." (PMID 41331848, 2025).
lung diseases (1 paper, 2016). "Moreover, TGF-β1 enhances phosphorylation of Smad2 and Smad3 in cells, leading to the TGF-β-dependent EMT and subsequent development and progress of fibrosis-related lung diseases." (PMID 27271612, 2016).
lupus nephritis (1 paper, 2016). Glomerulonephritis in the context of systemic lupus erythematosus. "Taken together, we presume that TWEAK mediated positive regulation of TGF-β signaling may have a promoting role in kidneys remodeling in lupus nephritis; the phosphorylation of p38 MAPK and Smad2 might be also included in the downstream of TWEAK-TGF-β signaling pathway." (PMID 27365897, 2016).
lymphoma (1 paper, 2013). A malignant (clonal) proliferation of B- lymphocytes or T- lymphocytes which involves the lymph nodes, bone marrow and/or extranodal sites. "Furthermore, it has been shown that miR-155 targets Smad2 mRNA in the monocytic cell line THP1 as well as Smad5 mRNA in lymphoma cells." (PMID 23554893, 2013).
malignant mesothelioma (1 paper, 2022). A malignant neoplasm of the pleura or peritoneum, arising from mesothelial cells. "YAP has been shown to form complexes in the nucleus involving Smad2/3, at least in malignant mesothelioma cells with deleted LATS35." (PMID 35246520, 2022).
medulloblastoma (1 paper, 2023). A malignant, invasive embryonal neoplasm arising from the cerebellum. "The results showed that Smad2 + 3, Smad4, Bcl2, and Caspase3 expression was changed in SHH medulloblastoma cell lines DAOY regardless of overexpression or knockdown of VASH2, indicating that VASH2 expression in myeloblasts may be mediated by affecting downstream indicators of TGFβ pathway." (PMID 37821528, 2023).
mucosal melanoma (1 paper, 2025). A melanoma that arises from a mucosal site. "Targeting SMAD2 and p38 MAPK pathways may further improve the outcome of mucosal melanoma." (PMID 39757723, 2025).
Myelodysplasia (1 paper, 2020). Clonal hematopoietic stem cell disorders characterized by dysplasia (ineffective production) in one or more hematopoietic cell lineages, leading to anemia and cytopenia. "We earlier used luspatercept and RAP‐536 protein traps for certain Smad2/3‐pathway ligands to implicate Smad2/3‐pathway overactivation in dysregulated erythroid differentiation associated with murine β‐thalassaemia and myelodysplasia." (PMID 32351032, 2020).
myocardial disease (1 paper, 2023). "In cardiac models of myocardial disease, SMAD2 inhibition protects against cardiac dysfunction, preventing cardiac fibrosis and cardiomyocyte hypertrophy, raising the possible therapeutic options for treating myocardial and valvular disease by targeting canonical TGFβ signaling." (PMID 37908840, 2023).
pancreatic adenocarcinoma (1 paper, 2017). "A recent report has shown that silencing Nrp1 diminished TGFβ signaling in pancreatic adenocarcinoma cells, but also inhibited TGFβ1-induced Smad2 phosphorylation in endothelial cells (HUVECs) and blocked endothelial to mesenchymal transition and fibrosis." (PMID 28938007, 2017).
pneumococcal infection (1 paper, 2018). Infections with bacteria of the species streptococcus pneumoniae. "Moreover, SPY1 vaccination elevated the levels of Smad2/3 and phosphor-Smad2/3 and downregulated the negative regulatory factor Smad7 in a time-dependent manner during pneumococcal infection, and these changes were reversed by P17 treatment." (PMID 30116243, 2018).
pneumonia (1 paper, 2020). An acute, acute and chronic, or chronic inflammation focally or diffusely affecting the lung parenchyma, caused by an infection in one or both of the lungs (by bacteria, viruses, fungi, or mycoplasma.). "We similarly found an expansion of circulating fibrocytes in patients with pneumonia and ARDS, which disproportionately expressed myofibroblast markers and expressed phosphorylated SMAD-2/3, evidence of TGF-β receptor signaling." (PMID 32460694, 2020).
polyp (1 paper, 2018). A usually exophytic mass attached to the underlying tissue by a broad base or a thin stalk.
prostate tumor (1 paper, 2017). "In particular, we found primarily overexpression of CTNNB1, CDH1, SMAD2, SMAD3, TCF3, LEF1 in younger patients and overexpression of SNAI1 and underexpression of KRT5, KRT19, OCLN, CDH2 and MUC1 which clearly indicates different characteristics of prostate tumor in younger vs older patients." (PMID 29206234, 2017).
pseudoexfoliative glaucoma (1 paper, 2021). "Interestingly, hsa-miR-26b-5p has recently been involved in pseudoexfoliative glaucoma through interaction with the TGFR1 and TGR2 part of SMAD2." (PMID 34063878, 2021).
psoriasis (1 paper, 2016). An autoimmune condition characterized by red, well-delineated plaques with silvery scales that are usually on the extensor surfaces and scalp. "The increased susceptibility to IMQ-induced psoriasis of GILZ-Tg mice was significantly associated with skin-specific over-activation of TGF-β1-mediated signaling via SMAD2/3." (PMID 27934944, 2016).
radiation-induced dermatitis (1 paper, 2025). "Exosomes derived from adipose-derived stem cells alleviate acute radiation-induced dermatitis by enhancing hyaluronic acid synthase 1 expression and activating the TGF-β/Smad2/3 pathway, thereby promoting skin regeneration and repair." (PMID 40394699, 2025).
rectal adenocarcinoma (1 paper, 2019). "Collectively, the results indicate that TIPE2 could modulate autophagy through the TGF‐β/Smad2/3 signalling pathway in human rectal adenocarcinoma cells." (PMID 30637920, 2019). "TIPE2 overexpression decreased autophagy by reducing the expression levels of p‐Smad2, p‐Smad3, and transforming growth factor‐beta (TGF‐β) in rectal adenocarcinoma cells, however, TIPE2 knockdown showed opposite effects." (PMID 30637920, 2019). "In conclusion, TIPE2 could regulate the proliferation, migration, and invasion of human rectal adenocarcinoma cells through Wnt/β‐Catenin and TGF‐β/Smad2/3 signalling pathways." (PMID 30637920, 2019). "Furthermore, the present study indicates that TIPE2 could mediate the proliferation, migration, and invasion of human rectal adenocarcinoma cells through Wnt/β‐Catenin and TGF‐β/Smad2/3 signalling pathways." (PMID 30637920, 2019).
renal (cystic) disease (1 paper, 2017). "In renal (cystic) disease, compensatory hyperfiltration and increased shear stress might contribute to induced SMAD2/3 activation, a well-known factor in the control of epithelial cell plasticity and fibrosis." (PMID 28168444, 2017). "Increased SMAD2/3 activation and increased TGF-β signaling has been shown in several animal models for renal cystic disease and patient-derived tissues." (PMID 28168444, 2017).
Renal atrophy (1 paper, 2020). Atrophy of the kidney. "Indeed, using the TRPM7 inhibitor NS8593 suppressed TRPM7 expression and cell proliferation both in tubular epithelial cells and interstitial cells, prevented upregulation of Smad2/Smad3 signaling, and attenuated renal atrophy and fibrosis." (PMID 32047249, 2020).
renal tumors (1 paper, 2010). "We measured protein expression of SMAD2, SMAD3, phospho-SMAD3 (pSMAD3) and FLCN in renal tumors from BHD patients (n = 11) and normal human kidney tissue (n = 5)." (PMID 20573232, 2010).
rheumatoid arthritis (1 paper, 2023). A chronic, systemic autoimmune disorder characterized by inflammation in the synovial membranes and articular surfaces. "This study investigated the detailed mechanisms that SMAD2 regulates the pyroptosis of FLS and secretion of inflammatory factors in rheumatoid arthritis." (PMID 37559090, 2023). "Whether SMAD2 decreased and pyroptosis of FLS enhanced in the early stage of rheumatoid arthritis similar to our results is still unclear, we will investigate this further in the future." (PMID 37559090, 2023).
sarcoglycanopathy (1 paper, 2016). Deficiencies or mutations in the genes for the sarcoglycan complex subunits. "Recently, a link between a sarcoglycanopathy in muscles and excessive TGFβ signaling was described that is mediated through SMAD2-325." (PMID 26939788, 2016).
sarcoidosis (1 paper, 2015). Sarcoidosis is a multisystemic disorder of unknown cause characterized by the formation of immune granulomas in involved organs. "The serum levels of TGF-β1 (p = 0.03), Smad2 (p = 0.01), and VEGF-A (p = 0.0002) were significantly higher in sarcoidosis patients compared to healthy controls." (PMID 26445225, 2015).
sarcoma (1 paper, 2020). A usually aggressive malignant neoplasm of the soft tissue or bone. "In conclusion, our data provide novel insight on the role of miR-3148-SMAD2-TGFβ axis during malignant transformation of hMSCs into sarcoma-like cancer and suggest therapeutic approaches targeting miR-3148/SMAD2/TGFβ pathway as plausible therapeutic strategy." (PMID 32922961, 2020). "To highlight the clinical relevance of our findings, we examined the expression of SDMAD2 in the Memorial Sloan Kettering Cancer Center and Broad Institute (SKCC/BI) soft tissue sarcoma dataset, which revealed significant downregulation of SMAD2 in 47% of sarcoma patients in these cohorts." (PMID 32922961, 2020).
skin squamous cell carcinoma (1 paper, 2012). A carcinoma arising from the squamous cells of the epidermis. "Recently, Hoot and colleagues found that Smad2, but not Smad3, was frequently lost in 83 patients with skin squamous cell carcinoma." (PMID 22539990, 2012).
soft tissue sarcoma (1 paper, 2020). A malignant neoplasm arising from muscle tissue, adipose tissue, blood vessels, fibrous tissue, or other supportive tissues excluding the bones. "In agreement with our data, SMAD2 expression was downregulated in 47% of patients with soft tissue sarcoma." (PMID 32922961, 2020).
T-cell lymphoma (1 paper, 2025). "The β-catenin-LINC00183-miR-371b-5p-Smad2/LEF1 axis promotes T-cell lymphoma progression and chemoresistance, as seen in T-cell lymphoblastic lymphoma." (PMID 40024178, 2025).
tapeworm infections (1 paper, 2023). "This suggests that tapeworm infections could initiate the TGF-β/Smad signaling pathway, upregulate TβRI, TβRII, and Smad2/3, and in turn induce the host to secrete a large amount of IL-17A, thus stimulating predominantly Th17-mediated immune responses." (PMID 36985175, 2023).
thoracic cancer (1 paper, 2018). A primary or metastatic malignant neoplasm affecting the tissues of the thorax. "Additionally, JQ1 suppressed BRD4, c-MYC, Collagen I, TGF-β, p-NF-κB p65, p-Smad2 and p-Smad3 expressions after irradiation, repressed proliferation and transdifferentiation of lung fibroblasts, and impaired clonogenic survival of thoracic cancer cells." (PMID 29343723, 2018).
venous ulcers (1 paper, 2025). "Some studies have shown that inhibition of TGFβ in chronic wounds have demonstrated inhibition in keratinocytes of nonhealing venous ulcers thus showing a decreased expression of TGFβ receptors, loss of Smad2 and deregulation of TGFβ target genes." (PMID 40495632, 2025).
Ventricular arrhythmia (1 paper, 2021). "The data suggested that ALK4 haplodeficiency exerted beneficial effects on inflammatory response and reduced the occurrence of ventricular arrhythmia post-MI by decreasing Smad2/3 phosphorylation." (PMID 34214050, 2021).
ZIKV infection (1 paper, 2020). "In vitro, we found that ZIKV infection reduced Foxp3 expression in EL‐4 cells, as well as Smad4 in addition to the reduced phosphorylation of Smad2 and Smad3." (PMID 32057179, 2020). "We showed that overexpression of Smad2 significantly enhanced P‐Smad2 as well as Foxp3 expression level, and ZIKV infection still significantly reduced level of P‐Smad2, P‐Smad3, Smad4 and Foxp3." (PMID 32057179, 2020). "ZIKV infection did not affect Smad2 and Smad3 expression, but significantly down‐regulated Smad4 expression as well as P‐Smad2 and P‐Smad3 (P < .05)." (PMID 32057179, 2020). "However, compared to ZIKV infection in mock transfection (no Smad2 overexpression), overexpression of Smad2 significantly increased level of Smad3, P‐Smad3, Smad4 and Foxp3." (PMID 32057179, 2020).
tumor (675 papers, 1998 to 2026). "The coworking network between PEG10 and MYC promotes that Smad2/3 and Snail are translocated into the nucleus, which is known to be a hallmark for the beginning and maintenance of tumor growth, survival and migration." (PMID 38204280, 2024). "The existence of feedback regulation was also noted: extracellular vesicles, derived from M2 macrophages, also contained miR-21-5p, which mediated the expression of EMT-associated genes: N-cadherin, α-SMA, Snail, and p-SMAD2 in tumor cells." (PMID 38794298, 2024). "Conversely, KRAS (p = 2.67e−90), FBXW7 (p = 1.29e−14), BRAF (p = 9.32e−8), GNAS (p = 2.54e−29), and SMAD2 (p = 3.93e−5) mutated tumors were significantly more common in MSLN high expressing tumor samples versus MSLN low expressing tumor samples." (PMID 39174744, 2024). "Loss of SMAD4/DPC4 tumour suppressive activity in PDAC leads to the acquisition of oncogenic function of SMAD2/3 and the associated deleterious effects." (PMID 37685308, 2023). "Salvianolic acid B inhibits the TGF-β pathway through downregulation of SMAD2/3/4 expression, which in turn inhibits the activation of tumour-associated fibroblasts and reshapes the tumour microenvironment." (PMID 37685308, 2023). "In conclusion, this work reveals that SMAD4 inactivation in PDAC not only results in a loss of SMAD4 tumor suppressive function but is concomitant to the oncogenic gain-of-function of SMAD2 and SMAD3." (PMID 36207615, 2022). "Surprisingly, the levels of phosphorylated SMAD2 were significantly lower in KIT-expressing versus KIT-deficient tumor cells." (PMID 35842424, 2022). "ILF3-AS1 inhibition caused marked reduction in SMAD2 levels in tumor tissues, whereas miR-132-3p expression was upregulated in xenografted mice." (PMID 33511320, 2021). "By concomitant deletion of PTEN and SMAD2/3, we have demonstrated that SMAD2/3 restrains tumor proliferation of PTEN-deficient organoids." (PMID 34638474, 2021). "ENST00000521666.1, a hyaluronan mediated motility receptor antisense RNA 1 (HMMR-AS1) transcript codes the antisense for HMMR, which is implicated with adverse tumor progression via the TGF-beta/Smad2 signaling pathway." (PMID 34771513, 2021). "The mutations of SMAD2 disrupts a famous tumor associated pathway named transforming growth factor β-Smad signaling pathway." (PMID 34513841, 2021). "Conversely, high Smad2 and Smad4 expression was linked to low tumor grade (p = 0,003, p = 0.048, respectively), and low tumor stage (p < 0.001, p = 0.003, respectively)." (PMID 31238579, 2019). "In our study, Nodal derived by tumor cells activated the Smad2 signaling in fibroblasts and the phosphorylated Smad2 was associated with Snail in promoting the activation of fibroblasts." (PMID 31167491, 2019). "Decrease or loss of Smad2 and Smad4 was significantly associated with advanced tumor stage (p < 0.001, p = 0.003, respectively)." (PMID 31238579, 2019). "Aberrant activation of AKT, ERK, STAT3, and Smad2/3 was reported to be closely associated with hepatocarcinogenesis and tumor progression 13-16." (PMID 31754332, 2019). "Since the two important tumor suppressor genes, SMAD2 and SMAD4 are located on this part of chromosome, the loss of chromosome 18q inactivates this pathway and promotes the evasion of apoptosis and cell proliferation." (PMID 31827763, 2019). "As compared to CD133− patients, tumor cells in CD133+ patients demonstrated high levels of TGF-β/p-Smad2 as well as EMT-like alteration, characterized by loss of E-Cadherin and expression of Vimentin and S100A4." (PMID 29510695, 2018). "We found that NRP1 shRNA expressing KRASmt tumor cells caused increased cell viability by decreasing SMAD2 phosphorylation." (PMID 29018205, 2017).